ERG (ETS transcription factor ERG)
Diseases named in the same sentence as ERG in open-access papers (continued):
Sharing a sentence is not in itself a finding about the gene and the disease.
prostate tumors (continued). "TMPRSS2::ERG was only identified by FusionInspector in prostate tumors or normal prostate, reflecting both this fusion’s high tissue specificity and FusionInspector’s high specificity of fusion calling." (PMID 37323575, 2023). "Expression of CXCR4 is under regulation by the ERG transcription factor, which is typically overexpressed in prostate tumors with a TMPRSS2-ERG gene fusion." (PMID 38239314, 2023). "FOXO1 also binds to and inhibits the ERG transcription factor, which is overexpressed in about 50% of early prostate tumors, and its deletion promotes tumors in mice with high ERG levels." (PMID 36768610, 2023). "Each of the five TCGA prostate normal samples containing TMPRSS2::ERG were found with TMPRSS2::ERG in their matching prostate tumor samples, likely due to tumor-in-normal contamination." (PMID 37323575, 2023). "The ETS transcription factor ERG is aberrantly expressed in approximately 50% of prostate tumors due to chromosomal rearrangements such as TMPRSS2/ERG." (PMID 37956771, 2023). "Based on RNA-seq analysis of HNF1B knockdown, we next curated a panel of 25-gene as HNF1B co-expression signature and measured the degree of their expression correlation with ERG in prostate tumors." (PMID 36443337, 2022). "Primary prostate tumors that harbor a TMPRSS2-ERG gene fusion possess a unique set of active cis-regulatory elements (CREs) compared to tumors lacking this genomic rearrangement, suggesting a potential link between ERG and cistromic reprogramming." (PMID 36212399, 2022). "ERG expression promotes prostate tumor formation and luminal epithelial cell fates when combined with PI3K/AKT pathway activation, however the mechanism of synergy is not known." (PMID 34314419, 2021). "The TMPRSS2/ERG gene rearrangement occurs in 50% of prostate tumors and results in expression of the transcription factor ERG, which is normally silent in prostate cells." (PMID 34314419, 2021). "Compared to ERG-negative and benign tumor, USP9X expression is also increased in ERG-positive prostate tumor." (PMID 34112167, 2021). "The TMPRSS2/ERG gene rearrangement found in prostate tumors results in ERG expression in prostate cells, a cell type where ERG is not normally expressed." (PMID 33554122, 2021). "ERG is overexpressed in 40%–50% of primary prostate tumours, with ETS gene rearrangements—mainly TMPRSS2-ERG fusion (>90% ETS rearrangements)—described in 30%–50% of patients with newly-diagnosed, untreated PCa." (PMID 32545454, 2020). "Along with this, it is attractive to observe that the TMPRSS2:ERG fusion gene is found in approximately 50% of prostate tumours of whites whereas is infrequent in black and Asian men." (PMID 32774170, 2020). "In human CaP, gene fusion between androgen responsive regulatory elements at the 5'-untranslated region of TMPRSS2 and ETS-related genes (ERG) is present in at least 50% of prostate tumors." (PMID 31303963, 2019). "Together, our results provide new insights into prostate tumorigenesis further refining the sub-classes of ERG-negative and ERG-positive prostate tumor types." (PMID 30150711, 2018). "Further advances in gene expression profiling and bioinformatics have revealed the overexpression of ERG in prostate tumors that led to the discovery of TMPRSS2-ERG fusion." (PMID 29690565, 2018). "An early and common event in prostate tumour development involves a translocation that forms a TMPRSS2:ERG fusion, bringing the ERG transcription factor under transcriptional control of the more active TMPRSS2 promoter." (PMID 29892050, 2018). "The candidate CNV genes found in TCGA dataset show comparable alteration frequency in an independent whole genome sequencing dataset, which includes 7 ERG-positive and 7 ERG-negative prostate tumors (CPDR dataset)." (PMID 30150711, 2018).
prostate tumors (continued). "According to the type of single alteration, single ERG positive immunostaining was found in 30.8% of GS = 6, 14.6% of GS = 7 and in 15.4% of GS ≥ 8 prostate tumor samples (Pearson Chi-Square, p = 0.062)." (PMID 29088771, 2017). "In order to analyze the potential relationship of SLC45A3 and PTEN alterations with the ERG pathway activation, prostate tumors were divided in 2 groups according to the results of ERG IHC: ERG positive (n = 103) and ERG negative (n = 117)." (PMID 29088771, 2017). "In order to analyze the impact of SLC45A3 and PTEN alterations on ERG pathway activation, prostate tumors were divided in 2 groups depending on ERG immunohistochemical expression being positive (n = 103) or negative (n = 117)." (PMID 29088771, 2017). "More studies are required to determine the prognostic value of ERG in different ethnic groups, particularly in African American and Asian patients with prostate tumors harboring less TMPRSS2/ERG fusion." (PMID 27191272, 2016). "Surprisingly, we found a positive correlation between the transcript levels of TRIM25 and ERG in ERG-positive prostate tumors in the RNA-seq data from The Cancer Genome Atlas (TCGA) consortium." (PMID 27626314, 2016). "We showed that TMPRSS2-ERG fusions regulate CXCR4 expression in prostate tumors; thus, androgen induced ERG expression transcriptionally regulates CXCR4 expression in PC cells." (PMID 27809841, 2016). "Although induction of the tumor suppressive miR-200b subfamily of miRNA by oncogenic ERG appears to be counterintuitive, it is consistent with the slow-growing nature of the vast majority of primary prostate tumors." (PMID 27191272, 2016). "Conversely, ERG has been reported to indirectly reprogram the androgen receptor cistrome in prostate tumors." (PMID 26938745, 2016). "The fusion of TMPRSS2-ERG leads to over-expression of ERG in the prostate gland; this promotes prostate tumour initiation and progression." (PMID 25933120, 2015). "Transcriptional upregulation of the chemokine receptor 4 gene (CXCR4) in organ-confined tumor cells that overexpress the ETS-related gene ERG (i.e., TMPRSS2-ERG fusion) increases the motility of prostate tumor cells in vitro." (PMID 25884570, 2015). "The TMPRSS2/ERG fusion is an important cellular rearrangement occurring in 50% of localised prostate tumours and ERG protein expression using IHC has been shown to be a robust surrogate for detecting the gene fusion." (PMID 26504789, 2015). "C-X-C chemokine receptor type 4 (CXCR4) is a downstream target of ERG, whose upregulation in prostate-tumor cells contributes to their migration from the prostate gland." (PMID 25884570, 2015). "For example, the TMPRSS2/ERG gene fusion was identified as a frequent chromosomal rearrangement present in a subgroup of prostate tumors that leads to ERG transcription factor overexpression." (PMID 24708576, 2014). "For example, cysteine-rich secretory protein 3 (CRISP3) gene expression was found to be associated with the ERG condition, since it was overexpressed in TMPRSS2-ERG fusion-positive prostate tumors as compared to normal tissue." (PMID 24739220, 2014). "PTEN deletion and the TMPRSS2:ERG rearrangement are the two most common genomic aberrations in prostate tumors." (PMID 24642271, 2014). "For example, USP9X inhibitor (WP1130) downregulated ERG levels and inhibited cell proliferation and migration in prostate tumors." (PMID 24739220, 2014). "A rearrangement of chromosome 21 that results in fusion of the TMPRSS2 and ERG genes occurs in approximately 50% of prostate tumors." (PMID 24642271, 2014). "Although 3p13 is deleted in approximately 20% of prostate tumors, there is an enrichment of 3p13 deletions in ERG positive tumors." (PMID 25155515, 2014). "The most common fusion involves androgen-regulated TMPRSS2 gene with an oncogenic ETS family transcription factor ERG gene, which is reported in 50% of surgical prostate tumors." (PMID 24133629, 2013).
prostate tumors (continued). "Overexpression of ERG transcription factor due to genomic ERG-rearrangements defines a separate molecular subtype of prostate tumors." (PMID 23555854, 2013). "The aim of our study was to provide a mechanistic explanation for the transcriptional activation of TDRD1 in ERG rearrangement-positive prostate tumors." (PMID 23555854, 2013). "Since ERGIC1 and TMED3 expression correlated with ERG expression levels in ERG positive primary prostate tumors, the potential effect of their expression on ERG mRNA expression was studied in VCaP cell line." (PMID 22761906, 2012). "Frizzled-4 (FZD4, a Wnt receptor) is co-expressed in human prostate tumor samples with the ETS-related gene (ERG)." (PMID 24212796, 2011). "Most tumors, which would have been classified as ETS negative based on the exclusive assessment of the few ETS genes known to be translocated in prostate tumors (i.e., ERG, ETV1 and ETV4) had in fact significantly alterations of other ETS factors." (PMID 20479932, 2010). "ERG rearrangements are found in nearly 40%–70% of prostate tumours." (PMID 40165885, 2025). "Likewise, the TMPRSS2:ERG gene fusion, commonly assessed in platforms like MiPS, arises from AR-driven transcriptional activity and reshapes the transcriptomic landscape of prostate tumors." (PMID 40649790, 2025). "FASN protein expression has previously been shown to be increased in prostate tumors harboring underlying ERG gene rearrangements compared with those without ERG rearrangements." (PMID 38112617, 2024). "ERG expression was described in prostate tumors but was not reported to be associated with ovarian carcinomas." (PMID 37830603, 2023). "Indeed, Nguyen and colleagues identified and characterized age-dependent prostate tumors in transgenic mice expressing high levels of ERG." (PMID 35267426, 2022). "Therefore, further investigation is needed to verify the role of this lncRNA in ERG-positive prostate tumors, in which it is reported that the expression of cell cycle-related genes is negatively regulated by ERG." (PMID 33672425, 2021). "Notably, we found that prostate tumors of ERG/PTEN mice express higher level of miR-322, the murine orthologous of miR-424, than prostatic tissue from wild type (WT) mice." (PMID 33500545, 2021). "ERG expression in prostate tumor models can promote luminal epithelial cell fates, indicating that this could be part of the oncogenic function of ERG." (PMID 34314419, 2021). "The TMPRSS2/ERG rearrangement drives aberrant expression of ERG in 50% of prostate tumors." (PMID 33585247, 2020). "Similar to our results, it could be demonstrated that depletion of USP9X increased ERG ubiquitination and subsequently suppressed prostate tumor growth." (PMID 30700749, 2019). "Importantly, we found that prostate tumors from ERG/PTEN mice were highly enriched of stem-like cancer cells that formed large tumor-spheroids when plated in prostate-sphere culture conditions." (PMID 31143708, 2019). "While some studies did not found significant association between ERG fusion and disease progression, numerous studies reported positive correlation of ERG-negative prostate tumor type with disease progression." (PMID 30150711, 2018). "Inactivating point mutations and deletions of the ETS factor ERF were recently identified in about 4% of prostate tumors, and these mutations are able to recapitulate phenotypes of ERG overexpression; furthermore, ChIP-seq analyses indicate that ERF and ERG compete for binding throughout the genome." (PMID 30603056, 2018).
prostate tumors (continued). "Moreover, the combination of ERG expression and PTEN loss was higher in GG2 and GG3 groups (Pearson Chi-Square, p = 0.041), and the triple hit phenotype was higher in GG4 and GG5 prostate tumors (Pearson Chi-Square, p = 0.0003)." (PMID 29088771, 2017). "The most frequently rearranged member of this family is the Ets Related Gene (ERG), which is overexpressed through gene fusion with the 5′ untranslated region of the gene encoding Transmembrane protease, serine 2 (TMPRSS2) in ∼40% of prostate tumors." (PMID 27626314, 2016). "Surprisingly, they observed that NKX3.1 is directly controlled by ERG in prostate tumors." (PMID 26689514, 2015). "Prostate tumors positive for ERG-fusion are characterized by an upregulation of targets for the transcription factor ERG, which in turn may lead to upregulation of Polycomb genes, thus linking ERG-fusion to Polycomb repression." (PMID 25115192, 2014). "This provides a mechanistic rationale for the correlation between PI3K signaling and ERG expression in prostate tumors and identifies a novel mode of ETS regulation that might be exploited by future therapeutics." (PMID 24642271, 2014). "Thus, ESRP1 and ESRP2 expression could also be indirectly activated via androgen-regulation of the ERG transcription factor in prostate tumours containing the TMPRS22-ERG genetic fusion." (PMID 37752235, 2023). "Therefore, inhibiting ERG might represent an important step to improve treatment efficacy for patients with ERG-positive prostate tumors." (PMID 35267426, 2022). "Given the context-dependent role of CHD1 in prostate tumors, genes showing co-occurrence (SPOP or MAP3K7) or mutual exclusivity (ERG and PTEN) should also be considered as influence factors in these clinical studies." (PMID 36776288, 2023). "Fusion proteins involving TMPRSS2, particularly those involving ERG and other ETS family members, are common SV alterations in prostate tumors." (PMID 35715489, 2022). "Both transcriptional regulator ERG (ERG) and TEAD4 can interact with the YAP1 promoter and increase H3K9/14Ac acetylation which leads to increased YAP1 expression in prostate tumors." (PMID 31216773, 2019). "The most common of these rearrangements is the fusion of the ETS family member ERG to the promoter and 5′ UTR of the TMPRSS2 gene, occurring in approximately 50% of prostate tumors." (PMID 30603056, 2018). "Similar to the expression of P4hb/Pdi in Tg-ERG mouse prostates, a significant correlation of P4HB/PDI up-regulation was observed in ERG positive human prostate tumors." (PMID 28439080, 2017). "Interestingly, in keeping with our previous study, the “triple hit” immunohistochemical phenotype (ERG positive/SLC45A3 loss/PTEN loss) was strongly associated with high grade prostate tumors, while this phenotype was completely absent among cases with GS = 6 or GG1." (PMID 29088771, 2017). "In order to validate our previous results, we have analyzed the immunohistochemical expression of ERG, SLC45A3 and PTEN in a large, independent cohort of prostate tumors collected in nine TMA blocks." (PMID 29088771, 2017). "ETS-related gene (ERG) is an oncogene whose activation is one of the most common oncogenic alterations in PCa, occurring in over 50% of prostate tumors." (PMID 27626693, 2016). "Since ERGIC1 was highly expressed in most primary prostate tumors, and ERGIC1 silencing was able to downregulate ERG expression, it is an intriguing potential drug target especially for the ERG oncogene expressing tumors." (PMID 22761906, 2012). "Two ets related transcription factors observed in this study, ets-related gene (ERG) and Sam pointed domain ets transcription factor (SPEDF) are known to be upregulated in prostate tumor epithelial cells." (PMID 20426842, 2010). "We show that Nkx3.1 is directly controlled by ERG and ESE3 in prostate tumors and EZH2 contributes to its silencing." (PMID 20479932, 2010).
prostate tumors (continued). "We found frequent dysregulation of ETS genes with oncogenic (i.e., ERG and ESE1) and tumor suppressor (i.e., ESE3) properties in prostate tumors compared to normal prostate." (PMID 20479932, 2010). "The present study was designed to assess the feasibility of an immunomagnetic enrichment method for detecting circulating prostate tumor cells using research prototype TMA assays for prostate-specific mRNAs (PSA, PCA3 and the TMPRSS2:ERG gene fusion)." (PMID 20598135, 2010). "Our Drosophila model offers an opportunity to further examine the role of Ets21C in promoting tumorigenic signaling in non-mitotic cells and suggest a role for ERG in polyploid cells of prostate tumors." (PMID 40304035, 2025). "This molecular subtype falls within the wide category of ERG-negative prostate tumours accounting for 30%–60% of PCa cases." (PMID 40165885, 2025). "It was also recently determined that ERG (and the common TMPRSS2-ERG rearrangement) activates the transcriptional program regulated by YAP1, and that prostate-specific activation of either ERG or YAP1 in mice induces similar transcriptional changes and results in age-related prostate tumors." (PMID 36979713, 2023). "Pioneer transcription factors, including FOXA1, HOXB13, and GATA2, as well as the transcription factor ERG, have prominent roles to play in earlier, hormone-sensitive stages of the disease and in CRPC where AR signaling remains a mainstay of prostate tumor growth." (PMID 36212399, 2022). "In contrast, in prostate tumours without an ERG gene fusion event, the discrimination in Kaplan-Meier survival between the defined four different PDE4D7 categories was nonsignificant (logrank p = 0.08)." (PMID 31275657, 2019). "The detection of ERG expression in prostate tumors of non-BCR and BCR cases by NanoString assay was also corroborated by mRNA and protein expression analyses, using qRT-PCR and IHC, respectively." (PMID 31741711, 2019). "In this study, we systematically explored the genomic and molecular differences of gene fusions, somatic mutations, SCNAs, gene expression signatures and dysregulation of pathways in prostate tumors with or without ERG fusion using publicly available data." (PMID 30150711, 2018). "We found that the LSAMP gene that is frequently deleted in ERG-negative prostate tumors of African American men49, was often rearranged including fusion with ZBTB20 specifically in the ERG-negative group." (PMID 30150711, 2018). "Since we have characterized both common and group-specific genomic alterations with high frequency in ERG-positive and ERG-negative prostate tumors, we next examined the molecular portrait of the ERG-negative group based on the associated candidate genes." (PMID 30150711, 2018). "The observed molecular differences on gene fusions, somatic mutations and copy number alterations between ERG-positive and ERG-negative prostate tumors suggest both common and distinct mechanisms of prostate tumorigenesis." (PMID 30150711, 2018). "PTEN loss is two- to five-times more frequent among ERG-positive compared to ERG-negative tumors and we and other groups have reported that PTEN loss occurs subsequent to ERG rearrangement in the majority of prostate tumors." (PMID 28186998, 2017). "Regarding the ERG negative cases, single PTEN loss was found in 18, single SLC45A3 loss in 18, and the double PTEN/SLC45A3 loss in 10 prostate tumors." (PMID 29088771, 2017). "A recent study has found that obesity promotes the growth of ETS-related gene (ERG)-overexpressing prostate tumors but not that of ERG-negative tumors." (PMID 27604692, 2016). "Although TMPRSS2/ERG fusion is detected in approximately 50% of human prostate tumors, ERG transgenic mice do not develop prostate tumor spontaneously." (PMID 27191272, 2016). "USP9X expression is significantly upregulated in ERG-positive prostate tumours compared to ERG-negative and benign tumours." (PMID 25672900, 2015).